AMELX (amelogenin X-linked)
Description:
Plays a role in biomineralization. Seems to regulate the formation of crystallites during the secretory stage of tooth enamel development. Thought to play a major role in the structural organization and mineralization of developing enamel.
Synonyms: AMG; AMGX; AI1E; AIH1; ALGN; AMGL
Tractability: Antibody: UniProt places it where antibodies can reach, with high confidence; its Gene Ontology location is reachable by antibodies, with high confidence; UniProt predicts a signal peptide or a membrane-spanning region.
Gene: Protein-coding gene on chromosome X (11,293,413 to 11,300,761, forward strand). Ensembl gene ENSG00000125363.
Subcellular location: Secreted, extracellular space, extracellular matrix
Pathways (Reactome):
Metabolism of proteins: Post-translational protein phosphorylation; Regulation of Insulin-like Growth Factor (IGF) transport and uptake by Insulin-like Growth Factor Binding Proteins (IGFBPs)
Gene Ontology:
Molecular function: protein binding; structural constituent of tooth enamel; growth factor activity; hydroxyapatite binding; identical protein binding; calcium ion binding; protein homodimerization activity; sodium ion binding
Biological process: enamel mineralization; tooth mineralization; amelogenesis; biomineral tissue development; cell adhesion; chondrocyte differentiation; epithelial to mesenchymal transition; odontogenesis of dentin-containing tooth; osteoblast differentiation; positive regulation of collagen biosynthetic process; positive regulation of tooth mineralization; regulation of cell population proliferation; signal transduction; response to calcium ion; response to nutrient; response to xenobiotic stimulus
Cellular component: extracellular matrix; cell surface; endoplasmic reticulum lumen; non-collagenous component of interstitial matrix; basement membrane; endocytic vesicle; protein-containing complex
Homologues: Orthologues: chimpanzee AMELX (100% identical), macaque AMELX (99% identical), dog AMELX (92% identical), dog AMELY (88% identical), mouse Amelx (87% identical), rat Amelx (86% identical), pig AMELY (85% identical), tropical clawed frog amelx (42% identical). Paralogues in human: AMELY (88% identical).
Diseases named in the same sentence as AMELX in open-access papers:
AMELX is named in the same sentence as 21 diseases in open-access papers, as found by Europe PMC text mining. Sharing a sentence is not in itself a finding about the gene and the disease. The quoted sentences say what the papers report.
amelogenesis imperfecta (8 papers, 2017 to 2024). Amelogenesis imperfecta (AI) represents a group of developmental conditions affecting the structure and clinical appearance of the enamel of all or nearly all the teeth in a more or less equal manner, and which may be associated with morphologic or biochemical changes elsewhere in the body. "Several SNPs, for example, rs3796704 in the gene encoding enamelin (ENAM) or rs17878486 in AMELX, were previously associated with various dental problems, such as amelogenesis imperfecta or molar-incisor hypomineralization, despite being in non-coding regions." (PMID 36422720, 2023). "Mutations in the AMELX gene are associated with the development of amelogenesis imperfecta." (PMID 36422720, 2023). "Furthermore, mutations in AMELX led to the genetic and phenotypical diversity of X-linked amelogenesis imperfecta." (PMID 32587839, 2019). "Mutations in genes involved in enamel formation, such as enamelin (ENAM), amelogenin (AMELX), matrix metalloproteinase-20 (MMP-20) and kallikrein-related peptidase (KLK4), were associated with amelogenesis imperfecta." (PMID 28697775, 2017). "Mutations in AMELX, DLX3, LAMA3, LAMB3, and WDR72 were reported in both non-syndromic and syndromic amelogenesis imperfecta." (PMID 33672174, 2021).
dental caries (7 papers, 2015 to 2024). The decay of a tooth, in which it becomes softened, discolored, and/or porous. "The association of the SNP in AMELX (rs17878486) with dental caries was confirmed also in a meta-analysis." (PMID 36422720, 2023). "In conclusion, significant associations were found between the occurrence of dental caries, the SNP in AMELX (rs17878486), and some SNPs in KLK4 (rs198968, rs2235091, rs2242670, and rs2978642)." (PMID 36422720, 2023). "Both ENAM rs3796704 and AMELX rs17878486 polymorphisms had a significant association with dental caries risk in the Caucasian ethnicity and the studies including caries-free control group." (PMID 32375748, 2020). "The association between the mutations of LTF, ENAM, and AMELX genes and dental caries susceptibility has been shown in some studies." (PMID 32375748, 2020). "This meta-analysis evaluated the association of LTF, ENAM, and AMELX polymorphisms with dental caries susceptibility." (PMID 32375748, 2020). "This meta-analysis assessed the association between the common polymorphisms of LTF, ENAM, and AMELX and the risk of dental caries." (PMID 32375748, 2020). "In conclusion, our findings showed that rs946252 polymorphism in the AMELX gene is associated with dental caries susceptibility, although, the development of dental decay necessitates a complex interaction between environmental and genetic variables." (PMID 32587839, 2019). "The purpose of this study was to examine the association between dental caries and single-nucleotide polymorphisms in the AMELX gene." (PMID 32587839, 2019). "As many previous investigations demonstrated the significance of the AMELX gene in enamel formation, certain authors proposed an association between AMELX gene polymorphism and dental caries." (PMID 32587839, 2019). "Higher dental caries rate in women has been postulated as multifactorial, caused by social factors, hormonal changes, differing salivary composition and flow rate, and variants of the AMELX gene." (PMID 37805471, 2023). "Sensitivity analysis, however, indicated that AMELX (rs17878486) could be a risk factor for dental caries, which might have been hidden by other effective factors, namely, the ethnicity and type of selected controls." (PMID 36422720, 2023). "Therefore, the aim of the present study was to investigate the differences between caries-free individuals and those with dental caries in terms of two genes associated with dental caries, i.e., AMELX and ENAM." (PMID 36624859, 2022). "However, subgroup analysis showed an association between ENAM rs3796704 and AMELX rs17878486 polymorphisms and dental caries susceptibility in the Caucasian ethnicity and studies including caries-free individuals as the control group." (PMID 32375748, 2020). "In addition, two studies included in our meta-analysis showed an association between AMELX rs17878486 polymorphism and dental caries susceptibility." (PMID 32375748, 2020). "Therefore, there was a significant association between both polymorphisms of ENAM rs3796704 and AMELX rs17878486 and dental caries susceptibility in the Caucasian ethnicity and studies including caries-free individuals as the control group." (PMID 32375748, 2020). "In this investigation, we studied whether the SNP in AMELX is associated with dental caries in female and male Iranian adults using the tetra-primer ARMS-PCR." (PMID 32587839, 2019). "Our results show that the SNPs of the AMELX gene may be related with susceptibility to dental caries in Iranian adults." (PMID 32587839, 2019). "Interestingly, the C allele of the SNP in AMELX (rs17878486) was associated with a higher risk of dental caries in primary dentition (p = 0.015, OR = 2.05, 95% CI 1.09–3.84), while the opposite effect was observed in permanent dentition (p = 0.011, OR = 0.70, 95% CI 0.51–0.94)." (PMID 36422720, 2023).
dental caries (continued). "However, sensitivity analysis showed that AMELX rs17878486 polymorphism can be a risk factor for dental caries, but race and type of the control group are the factors influencing the relationship between AMELX rs17878486 polymorphism and the risk of dental caries." (PMID 36624859, 2022). "Therefore, it may point to the role of AMELX rs17878486 polymorphism in development of dental caries more than others." (PMID 32375748, 2020). "The literature review also shows that AMELX and KLK4 variabilities have been associated with dental caries more often than variabilities in other genes." (PMID 36422720, 2023). "Based on this study, we found that although the SNPs in AMELX and KLK4 are localized in intronic regions and their functional significance has not yet been determined, they are associated with susceptibility to dental caries in children." (PMID 36422720, 2023). "Dental caries in primary dentition was associated with SNPs in AMELX (rs17878486) and KLK4 (rs198968, rs2242670), and dental caries in permanent dentition with SNPs in AMELX (rs17878486) and KLK4 (rs2235091, rs2242670, rs2978642), (p ≤ 0.05)." (PMID 36422720, 2023). "However, the sensitivity analysis revealed that AMELX rs17878486 polymorphism could be a risk factor for dental caries but the ethnicity and type of selected controls were the effective factors on the association between AMELX rs17878486 polymorphism and risk of dental caries." (PMID 32375748, 2020). "Several previous studies have identified an association between several genes and dental caries, including genes related to enamel formation such as AMBN, AMELX, and ENAM; taste receptor genes such as TAS2R38, TAS1R2; immune-related genes such as HLA; and saliva genes such as MUC5B, PRH1." (PMID 38414691, 2024). "AMELX and KLK4 variants could be considered in the risk assessment of dental caries, especially in permanent dentition, in the European Caucasian population." (PMID 36422720, 2023). "In our meta-analysis on AMELX rs946252, AMELX rs17878486, AMELX rs6639060, and AMELX rs2106416 polymorphisms, none of them was associated with the risk of dental caries." (PMID 32375748, 2020). "The purpose of this study was to determine whether dental caries in Iranian adults is related to SNPs in the AMELX gene." (PMID 32587839, 2019). "Three prevalent genes are reportedly involved in development of dental caries namely the lactotransferrin (LTF), enamelin (ENAM), and amelogenin X (AMELX)." (PMID 32375748, 2020). "In this case–control study, 15 SNPs in ALOX15, AMBN, AMELX, KLK4, TFIP11, and TUFT1 genes were analyzed in 150 children with primary dentition and 611 children with permanent teeth with/without dental caries from the European Longitudinal Study of Pregnancy and Childhood (ELSPAC) cohort." (PMID 36422720, 2023).
enamel hypoplasia (3 papers, 2015 to 2024). "In humans, variety of mutations in AMELX gene are associated with enamel hypoplasia and/or hypomaturation (OMIM 301200)." (PMID 25815730, 2015). "In addition, a duplication of uncertain significance including both HCCS and AMELX was identified in a male with corneal anomalies, glaucoma, an atrial septal defect, and enamel hypoplasia along with a family history of developmental ocular disorders consistent with X-linked inheritance." (PMID 39766903, 2024).
ameloblastoma (1 paper, 2024). The most common odontogenic tumor, arising from the epithelial component of the embryonic tooth and usually affecting the molar-ramus region of the mandible or maxilla. "In conclusion, our study demonstrates similarities in AMELX and ODAM expression between craniopharyngioma and ameloblastoma, supporting their shared embryological origins." (PMID 39451638, 2024). "The immunohistochemical analysis of AMELX, ODAM, and CK19 across the 44 cases revealed distinct expression patterns between craniopharyngioma and ameloblastoma." (PMID 39451638, 2024).
cholangiocarcinoma (1 paper, 2021). A carcinoma that arises from the intrahepatic biliary tree (intrahepatic cholangiocarcinoma) or from the junction, or adjacent to the junction, of the right and left hepatic ducts (hilar cholangiocarcinoma). "The top-ranked somatic eQTL genes with missense mutations include USP29 in cholangiocarcinoma (CHOL) and AMELX, CNTN5, and OR1L3 in lymphoid neoplasm diffuse large B-cell lymphoma (DLBC)." (PMID 33691015, 2021).
tumor (2 papers, 2024). "Our findings revealed similarities in AMELX and ODAM expression between these two tumor types, supporting the hypothesis of a shared embryological origin from the oral ectoderm." (PMID 39451638, 2024). "Among odontogenesis related genes, AMBN is specifically expressed in T3, other genes including ENAM, AMELX and AMELY are not expressed in all the tumor cells." (PMID 39223689, 2024).
AMELX also shares sentences with these, for which no sentence is quoted: craniopharyngioma (1 paper); dental fluorosis (1); diffuse large B-cell lymphoma (1); Down syndrome (1); ectodermal dysplasia (1); genetic diseases (1); glaucoma (1); infection (1); lymphoid neoplasm (1); malocclusion (1); osteogenesis imperfecta (1); periodontitis (1); prostate carcinoma (1); septal defect (1); trisomy 21 (1).